NINJ2 (ninjurin 2)
Diseases named in the same sentence as NINJ2 in open-access papers (continued):
Sharing a sentence is not in itself a finding about the gene and the disease.
endometrial cancer (3 papers, 2021 to 2024). Primary or metastatic malignant neoplasm involving the endometrium (mucous membrane that lines the endometrial cavity). "We performed the case control study to investigate the relationship between five SNPs (rs118050317, rs75750647, rs7307242, rs10849390 and rs11610368) of NINJ2 gene and endometrial cancer risk in Chinese women." (PMID 33397383, 2021). "In this study, we did an association study between NINJ2 gene polymorphism and endometrial cancer risk in 351 endometrial cancer patients and 344 healthy controls." (PMID 33397383, 2021). "The NINJ2 gene polymorphism loci rs118050317 mutant allele C was associated with an increased risk of endometrial cancer." (PMID 33397383, 2021). "In conclusion, the NINJ2 gene polymorphism loci rs118050317 mutant allele C was associated with an increased risk of endometrial cancer and there was significant higher quantity in serum of CEA, CA125 and AFP in cases than controls." (PMID 33397383, 2021). "The underlying mechanism of NINJ2 gene involving in endometrial cancer need to be researched next step." (PMID 33397383, 2021). "In the NINJ2 gene, rs118050317 polymorphism was related to endometrial cancer risk." (PMID 38929750, 2024). "We conducted an association analysis between NINJ2 gene polymorphism and endometrial cancer risk." (PMID 33397383, 2021). "So we speculate the rs118050317 C allele of NINJ2 through regulate the IL-6 expression to influence the ERK-NF-κB signaling pathway of endometrial cancer growth." (PMID 33397383, 2021). "In this study we investigated whether alterations in the NINJ2 gene can influence the risk of endometrial cancer." (PMID 33397383, 2021). "Five SNPs rs118050317, rs75750647, rs7307242, rs10849390 and rs11610368 of NINJ2 gene were genotyped in 351 endometrial cancer patients and 344 healthy controls." (PMID 33397383, 2021).
Hypertension (3 papers, 2011 to 2017). The presence of chronic increased pressure in the systemic arterial system. "Among the vascular risk factors explored in this study (e.g., hypertension, DM, hyperlipidemia, smoking, and high BMI), hyperlipidemia is the only one significantly modify the association between NINJ2 polymorphisms and the risk of AD." (PMID 21674003, 2011).
breast carcinoma (2 papers, 2015 to 2025). "Since both NINJ1 and NINJ2 are found to be over-expressed in several types of cancer, including breast cancer, targeting their interaction may be a feasible approach for cancer therapeutic development." (PMID 40136650, 2025). "In the current study, we generated several peptides derived from the N-terminus of NINJ1 and NINJ2 and showed that peptides targeting cell adhesion or the NINJ1-NINJ2 complex can elicit growth suppression in breast cancer cells." (PMID 40136650, 2025).
colitis (2 papers, 2022 to 2026). Inflammation of the colon. "We focused on the NINJ2 gene, the expression of which increased more than fivefold in AID-overexpressing DLD-1 cells and decreased in colitis-induced CECs of AID-knockout mice, compared with those of wild-type mice." (PMID 42283489, 2026).
colon cancer (2 papers, 2019 to 2025). "NINJ2 associations with these RTKs were also detected in fresh human colon cancer tissue lysates." (PMID 31597121, 2019). "An underlying mechanism identified was the downregulation of the NINJ2 gene expression by the bacterial culture filtrate, which subsequently contributed to oxaliplatin resistance in colon cancer cells." (PMID 40567024, 2025). "Similar results were obtained in the primary human colon cancer cells (“pri-Can-1/-2/-3”), where lentivirus-mediated overexpression of NINJ2 (“NINJ2-OE”) increased MTT OD and BrdU incorporation." (PMID 31597121, 2019). "Quantitative analyses of blotting results of all twenty pairs of tissues confirmed that NINJ2 protein levels are significantly higher in colon cancer tissues (P< 0.05 vs. colon epithelial tissues)." (PMID 31597121, 2019). "Further, in the primary human colon cancer cells, derived from three different colon cancer patients (“pri-Can-1/-2/-3”), relatively high NINJ2 mRNA levels were detected." (PMID 31597121, 2019). "As shown, in both HT-29 cells and primary human colon cancer cells (“pri-Can-1”), NINJ2 co-immunoprecipitated with EGFR, PDGFRα, PDGFRβ and FGFR." (PMID 31597121, 2019). "NINJ2 mRNA levels in a total of twenty human colon cancer tissues (“Cancer”) and paracancer normal colon epithelial tissues (“Normal”) were analyzed." (PMID 31597121, 2019). "In line with the mRNA results, NINJ2 protein levels were significantly higher in HT-29 cells and primary colon cancer cells, as compared with its levels in the colon epithelial cells." (PMID 31597121, 2019). "The primary human colon cancer cells (“pri-Can-1/-2/-3”) were infected with the lentivirus with NINJ2 shRNA (“Seq3”)." (PMID 31597121, 2019). "Given that oxaliplatin has been reported to stimulate intracellular ROS production, the inhibition of ROS generation through NINJ2 gene downregulation might elucidate the resistance to oxaliplatin seen in colon cancer cells." (PMID 40567024, 2025). "Furthermore, NINJ2 mRNA and protein levels are high in human colon cancer tissues, but were extremely low in normal paracancer colon epithelial tissues." (PMID 31597121, 2019). "As shown, NINJ2 mRNA levels were significantly upregulated in the colon cancer tissues." (PMID 31597121, 2019). "Likewise, NINJ2 knockout inhibited primary human colon cancer cell growth in SCID mice." (PMID 31597121, 2019). "NINJ2 co-immunoprecipitated with multiple RTKs (EGFR, PDGFRα/β and FGFR) in CRC cells and human colon cancer tissues." (PMID 31597121, 2019). "We show that NINJ2 is overexpressed in established (HT-29) and primary CRC cells and in human colon cancer tissues." (PMID 31597121, 2019). "This minimal ROS generation by 5‐FU might explain the absence of resistance observed in colon cancer cells, even with NINJ2 gene downregulation." (PMID 40567024, 2025). "Thus, NINJ2 could possibly form a complex with multiple RTKs in CRC cells and human colon cancer tissues." (PMID 31597121, 2019).
coronary artery disease (2 papers, 2017 to 2021). "However, whether variants in NINJ2 are associated with coronary artery disease (CAD) is unknown." (PMID 34897030, 2021).
dementia (2 papers, 2011 to 2021). Loss of intellectual abilities interfering with an individual's social and occupational functions. "As a vascular susceptibility gene, the SNPs in NINJ2 were genotyped to test for the association between variants of NINJ2 and dementia risk." (PMID 33397383, 2021). "Five common (frequency >5%) haplotype-tagging single nucleotide polymorphisms (htSNPs) in NINJ2 were genotyped to test for the association between sequence variants of NINJ2 and dementia risk, and how vascular risk factors modify this association." (PMID 21674003, 2011). "First, the association between NINJ2 polymorphisms and dementia risk has not been explored previously." (PMID 21674003, 2011). "This study investigated the association between genetic polymorphisms of a vascular susceptibility gene, Ninjurin2 (NINJ2), and the risk of dementia, which has not been explored previously." (PMID 21674003, 2011). "Our findings suggested that NINJ2 polymorphisms played an important role in dementia risk, which has not been explored so far." (PMID 21674003, 2011).
injury (2 papers, 2017 to 2025). Damage inflicted on the body as the direct or indirect result of an external force, with or without disruption of structural continuity. "A study reported that nerve injury-induced protein 2 (NINJ2) deficiency, a cell adhesion molecule, resulted in alteration of lipids including CER which was increased in NINJ2-KO MCF7 cells." (PMID 41335598, 2025). "The study aimed to explore whether serum Ninjurin2 (for nerve injury-induced protein 2, NINJ2), a novel neurologic damage related protein, is associated with nerve injury and the occurrence of PHN." (PMID 29069724, 2017). "Thus, serum NINJ2 levels were correlated with nerve injury and particularly with nerve recovery." (PMID 29069724, 2017).
neuropathies (2 papers, 2021 to 2024). "NINJ2 protein in Schwann cells is promoting nerve regeneration after injury, therefore downregulating NINJ2 expression may contribute to neuropathies development." (PMID 34063061, 2021).
acute monocytic leukemia (1 paper, 2022). Acute monoblastic leukemia (AML-M5), is one of the most common subtypes of acute myeloid leukemia (AML) that is either comprised of more than 80% of monoblasts (AML-M5a) or 30-80% monoblasts with (pro)monocytic differentiation (AML-M5b). "We also measured the expression of NINJ2 gene in presence of LPS in THP-1 cells, a cell line derived from human monocytes isolated from a patient with acute monocytic leukemia." (PMID 36360183, 2022).
Anxiety (1 paper, 2022). Intense feelings of nervousness, tension, or panic often arise in response to interpersonal stresses. "Interestingly, although the communication between oligodendrocytes and neurons should exist widely, the Ninj2‐deficient mice only exhibited apparent depressive‐like behaviors, but not memory or recognition defects, or anxiety." (PMID 34787377, 2022).
bladder cancers (1 paper, 2025). "The GSEA results also indicated that low expression of the MACC1, GRB10 and MARCKS genes, along with high expression of the NINJ2 gene, were associated with tumourigenesis, including breast, pancreatic and bladder cancers." (PMID 39926275, 2025).
cocaine addiction (1 paper, 2020). "Twelve DEGs (Myct1, Gm21860, Ninj2, Fam183b, Lars2, Alkbh1, Fgf5, Frmd7, Tm6sf2, Wnt6, Batf3, and Clca1) were found to be regulated inversely among the overlap genes, which may be possible targets of RPA to disrupt the cocaine addiction process." (PMID 32489401, 2020).
demyelinating disease (1 paper, 2022). A broad group of disorders that affect the myelin sheaths that cover the neurons. "Although ligands or inhibitors of Ninj2 are still need to be fully developed, it could be considered as a therapeutic target for demyelinating diseases." (PMID 36438492, 2022).
depression (1 paper, 2022). "As cytokines were tightly associated with the onset of depression, we tested the expression levels of inflammatory cytokines and found that Ccl2 was the most significantly upregulated in the Ninj2‐deficient oligodendrocytes, compared to the WT cells." (PMID 34787377, 2022). "Loss of Ninj2 inhibits oligodendrocyte development and myelination by inducing TNFα‐mediated necroptosis, impairs neuron functions, and results in depression." (PMID 34787377, 2022). "These mechanistic insights into the modulation of depression by Ninj2 broadened the biological significance of oligodendrocytes in CNS, and provided a therapeutic target for depression in clinical studies." (PMID 34787377, 2022). "After data mining with the online database in the depression mice models, we chose Ninj2 as our research candidate, because of its predominant expression patterns in oligodendrocyte lineage cells." (PMID 34787377, 2022). "In our present study, to demonstrate the function of Ninj2 in depression, we generated oligodendrocyte‐specific Ninj2‐knockout mice to evaluate the effect of Ninj2 in depression." (PMID 34787377, 2022). "Taken together, in this study, we identified Ninj2 in oligodendrocytes as an inhibitory factor in the development of depression." (PMID 34787377, 2022). "This study thus illustrates the role of Ninj2 in the development of depression and myelination, reveals the relationship between oligodendrocytes and neurons, and provides a potential therapeutic target for depression." (PMID 34787377, 2022). "Therefore, we chose Ninj2 as the candidate, to explore its role in the development of depression." (PMID 34787377, 2022).
gastric adenocarcinoma (1 paper, 2025). "Next, to investigate the clinical correlation between NINJ2 and CD44 levels, we analyzed data from human gastric adenocarcinoma samples (n = 426) in The Cancer Genome Atlas (TCGA) and the oncoSG dataset using cBioPortal." (PMID 40518514, 2025).
gastric cancer (1 paper, 2025). A primary or metastatic malignant neoplasm involving the stomach. "The aim of this study was to investigate the mechanisms underlying resistance to ECF chemotherapy in gastric cancer, focusing on the role of the NINJ2 protein." (PMID 40518514, 2025). "Since CD44 and CD133 have also been identified as markers of gastric cancer stem cells, we investigated how the levels of both proteins correlated with NINJ2 expression." (PMID 40518514, 2025). "K/D of NINJ2 led to a significant decrease in VAV2 phosphorylation in ECF-R gastric cancer cells, which further reduced cell viability after ECF treatment." (PMID 40518514, 2025). "In patients with gastric cancer, NINJ2 expression is significantly elevated in those with progressive disease, and high NINJ2 expression correlates with a poor survival rate." (PMID 40518514, 2025). "Tumor spheroids derived from MKN-74 gastric cancer cells showed significantly increased NINJ2 mRNA levels." (PMID 40518514, 2025). "Our findings demonstrate that increased NINJ2 expression in chemoresistant gastric cancer cells leads to upregulation of CD44, which in turn promotes vimentin expression and enhances invasive and mesenchymal characteristics." (PMID 40518514, 2025). "Both NINJ2 isoform-1 and − 3 O/E gastric cancer cells showed increased cell cycle arrest, with inhibition of the G0/G1 phase to the S phase, resulting in anti-proliferative activity." (PMID 40518514, 2025). "To validate the clinical relevance of NINJ2 expression in patients with gastric cancer, we performed IHC staining for NINJ2 in human gastric cancer tissues and corresponding normal tissues." (PMID 40518514, 2025). "We used siRNA to specifically target NINJ2 in gastric cancer cells and investigated its role in chemoresistance." (PMID 40518514, 2025). "Taken together, our findings suggest that NINJ2 drives tumor aggressiveness and represents a promising therapeutic target for inhibiting both drug resistance and metastasis in gastric cancer." (PMID 40518514, 2025). "To investigate the mechanisms through which NINJ2 induces drug resistance, we performed a phospho-antibody array using NINJ2 O/E gastric cancer cells." (PMID 40518514, 2025). "We found that NINJ2 is rarely expressed in normal tissues, but has a pivotal role in conferring chemoresistance in gastric cancer cells." (PMID 40518514, 2025). "Collectively, these findings demonstrate that elevated NINJ2 expression in ECF-R gastric cancer cells drives chemoresistance by inducing cell cycle arrest and promoting invasiveness." (PMID 40518514, 2025). "Hence, NINJ2 represents a novel regulator of chemoresistance and shows excellent potential as a therapeutic target for overcoming chemoresistance in gastric cancer." (PMID 40518514, 2025). "Thus, NINJ2 antigens can be developed into specific targeted therapies for chemoresistant gastric cancer cells using siRNA with lipid nanoparticles, antibodies, peptide-pulse immune cells, or small molecules." (PMID 40518514, 2025). "To determine whether CD44 expression was increased by NINJ2, we generated stable gastric cancer cells overexpressing (O/E) NINJ2 isoform-1 and -3." (PMID 40518514, 2025). "To evaluate whether NINJ2 is involved in chemoresistance, we generated stable NINJ2 knockdown (K/D) ECF-R gastric cancer cells." (PMID 40518514, 2025). "Furthermore, MKN-74 and SNU-484 ECF-R human gastric cancer cells exhibited increased NINJ2 protein levels." (PMID 40518514, 2025). "Furthermore, most NINJ2+ cells in the ECF-R gastric cancer cells also highly expressed CD44, and most of the NINJ2− cells were also CD44− cells." (PMID 40518514, 2025). "We hypothesized that chemoresistance in gastric cancer cells could be synergistically suppressed by the NINJ2/CD133 dual knockdown." (PMID 40518514, 2025).
gastric cancer (continued). "Moreover, we explored whether targeting NINJ2 could enhance chemosensitivity and reduce relapse, providing potential for NINJ2 as a biomarker and therapeutic target to improve treatment outcomes for patients with gastric cancer." (PMID 40518514, 2025). "Therefore, we focused on NINJ2 as a novel biomarker of chemoresistance in gastric cancer." (PMID 40518514, 2025). "Conversely, NINJ2 isoform-1 and − 3 O/E significantly diminished the effectiveness of ECF treatment in gastric cancer cells." (PMID 40518514, 2025). "Next, we analyzed the clinical relevance of NINJ2 expression to patient survival using Kaplan–Meier analysis and log-rank testing with public datasets (GSE15459) of patients with gastric cancer." (PMID 40518514, 2025). "To define the role of NINJ2 in chemoresistance, CIC enrichment, and clinical outcomes, we developed ECF-resistant (ECF-R) gastric cancer cell lines and organoids." (PMID 40518514, 2025). "Our findings reveal that NINJ2, a surface protein, is highly expressed in ECF-R gastric cancer cells and patient-derived tumor organoids." (PMID 40518514, 2025). "ECF-R primary human gastric cancer cell lines (SNU-488 and SNU-520) and metastatic human gastric cancer cell lines (MKN-28/74, MKN-74, MKN-45, and SNU-668) showed consistently and significantly increased NINJ2 mRNA levels." (PMID 40518514, 2025). "Furthermore, NINJ2 isoform-3, but not isoforms 1 and 2, was mainly expressed in ECF-R gastric cancer cells." (PMID 40518514, 2025).
hypopharyngeal cancers (1 paper, 2022). Carcinoma, predominantly squamous cell, arising from the epithelial cells of the hypopharynx. "These might explain somewhat our results that NINJ2 overexpressed hypopharyngeal cancer cells were more sensitive to CDDP." (PMID 35841085, 2022). "Herein, we newly demonstrated that 4 genes (and the proteins) as the most powerful exploratory markers for response prediction to TXT, CDDP, and 5-FU- namely, AGR2, and PDE4D for TXT; NINJ2 and possibly RAB15 for CDDP, and CDC25B for 5-FU- in hypopharyngeal cancers." (PMID 35841085, 2022).
liver fibrosis (1 paper, 2025). "In a model of MCD-induced liver fibrosis, NINJ2 knockdown attenuated liver fibrosis." (PMID 40761743, 2025).
lung adenocarcinoma (1 paper, 2024). A carcinoma that arises from the lung and is characterized by the presence of malignant glandular epithelial cells. "The low expression levels of down-regulated DEGs PLA2G3, PCP4L1, NINJ2, MIR186, and KLRG1 were also statistically correlated with a shorter OS in lung adenocarcinoma." (PMID 38183079, 2024).